CSF2 (colony stimulating factor 2)
Diseases named in the same sentence as CSF2 in open-access papers (continued):
Sharing a sentence is not in itself a finding about the gene and the disease.
Sepsis (168 papers, 2010 to 2026). Sepsis is defined as life-threatening organ dysfunction caused by a dysregulated host response to infection. "Contrary, monocytic HLA-DR-guided immunostimulatory therapy with CSF2 (Granulocyte–macrophage colony-stimulating factor) or IFNγ, have shown promising results in patients with severe sepsis." (PMID 36829233, 2023). "Following sepsis, we tested candidate MK growth factors and observed decreased splenic expression of Tpo, Csf2, and Ccl5, while Il1b was unchanged and Il3 and Il6 were significantly increased." (PMID 35192546, 2022). "We found that Csf2 derived from tubular cells induced M0/M1-to-M2 differentiation and subsequently played a protective role in sepsis-induced AKI." (PMID 32733471, 2020). "Our result is also consistent with a randomized controlled trial of 39 patients with sepsis who had immune dysfunctions: Csf2 therapy in these patients was safe and effectively restored the immunocompetence of monocytes." (PMID 32733471, 2020). "Here, we found an unexpected role of Colony stimulating factor 2 (Csf2) in controlling macrophage transition in vitro and in a mouse model of sepsis induced by cecal ligation and puncture (CLP)." (PMID 32733471, 2020). "As Csf2 may serve as a potential therapeutic target for sepsis-induced AKI, host defense parameters, including circulating cytokines and the bacterial load, should be evaluated in a CLP model following Csf2 treatment." (PMID 32733471, 2020). "Because Csf2 promotes the transition from the M1 phenotype to the M2 phenotype in vitro, we also examined whether a Csf2 antibody or recombinant Csf2 could contribute to macrophage differentiation in a murine sepsis model." (PMID 32733471, 2020). "Therefore, it is reasonable to speculate that Csf2 could play a central role in mitigating sepsis-induced AKI." (PMID 32733471, 2020). "In sepsis-induced AKI, CSF2 secreted by injured TECs can facilitate the transition from M1 to M2 macrophages in a dose- and time-dependent mode." (PMID 37153766, 2023). "However, administration of recombinant mouse Csf2 protein could rescue mice with sepsis." (PMID 32733471, 2020). "However, the role of Csf2 in sepsis-induced AKI remains largely unknown." (PMID 32733471, 2020). "In summary, we investigated the regulatory function of Csf2 in sepsis-induced AKI and found that Csf2 secreted by HK-2 cells could promote macrophage transition toward the M2 phenotype via the p-STAT5 signaling pathway." (PMID 32733471, 2020). "We hypothesized that the Csf2 antibody may aggravate AKI and decrease survival in a sepsis model." (PMID 32733471, 2020). "In a murine model of sepsis-induced AKI, systemic CSF2 administration, not TIMP2, attenuates AKI severity and improves mouse survival through promoting alternative macrophage transition." (PMID 38421825, 2023).
pancreatic cancer (146 papers, 2007 to 2025). "In pancreatic cancer, CSF2 promotes polarization of cancer-associated macrophages and supports maintain metabolic homeostasis via the PI3K/AKT signaling pathway." (PMID 41154660, 2025). "At the transcript level, mRNA expression of Ccl2, Ccl7, Cxcl1, Cxcl3, and Csf2 was markedly downregulated in Ccn1‐deficient pancreatic tumors, whereas Cxcl5, Csf1, and Csf3 expression remained unchanged, and Ccl20 mRNA was elevated." (PMID 40287974, 2025). "By contrast, granulocyte macrophage (GM)-CSF (CSF-2) is commonly expressed in pancreatic cancer cells and has been linked to the generation of MDSC with immunosuppressive features." (PMID 27191744, 2016). "More studies targeting CSF-2/CSF-2R signaling are needed to assess the potential of immunotherapy in pancreatic cancer treatment." (PMID 39195299, 2024). "Mechanistically, Regnase-1 directly negatively regulated a variety of chemokines/cytokines important for MDSC recruitment and activation, including CXCL1, CXCL2, CSF2, and TGFβ, in pancreatic cancer cells." (PMID 37814340, 2023). "Among a variety of chemokines/cytokines known to recruit and/or generate MDSCs in tumor sites, we found significant elevations in Cxcl1, Cxcl2, Csf2, and Tgfb1 in the pancreatic tumor tissues of PKR mice." (PMID 37814340, 2023). "In human pancreatic tumors, GM-CSF (or CSF-2) is prominently expressed, compared to CSF-1." (PMID 27191744, 2016). "However, limited studies have reported on the inhibition of CSF-2/CSF-2R signaling in pancreatic cancer." (PMID 27191744, 2016). "Consistent with previous reports, we demonstrated that knockdown of Cxadr could facilitate AKT activation and E‐cadherin downregulation in pancreatic tumor cells.[8a] In addition, the mRNA levels of both Cxcl1 and Csf2 were also upregulated in step with AKT phosphorylation." (PMID 36453584, 2023). "Through upregulating Csf2, NLRX1 is potentially helpful in promoting immune recognition of pancreatic tumors." (PMID 37342194, 2023). "Curcumin effectively attenuated the inflammatory microenvironment of pancreatic cancer by modulating a complex signaling network that downregulates NLRP3, CASP1 and CSF2 while simultaneously regulating expression of key pro-inflammatory factors within interleukin family." (PMID 40535567, 2025).
autoimmune disease (142 papers, 2011 to 2025). A disorder resulting from loss of function or tissue destruction of an organ or multiple organs, arising from humoral or cellular immune responses of the individual to their own tissue constituents. "Pathogenic Th17 cells, with higher expression of Il17, Csf2, Il23r, and Il1r1, play a pivotal role in the pathogenesis of autoimmune disorders." (PMID 37716986, 2023). "One anti-cytokine autoimmune disease is pulmonary alveolar proteinosis caused by autoantibodies against GMCSF (CSF2)." (PMID 33763057, 2021). "Interestingly, CXCL13 and CSF2 have been associated with autoimmune diseases." (PMID 35784351, 2022).
glioma (124 papers, 2008 to 2026). A benign or malignant brain and spinal cord tumor that arises from glial cells (astrocytes, oligodendrocytes, ependymal cells). "CSF2-deficient human glioma cells encapsulated in cell-impermeable hollow fibres and transplanted to mouse brains, failed to attract microglia, but stimulated astrocyte recruitment." (PMID 32390004, 2020). "The expression of CSF2 (encoding granulocyte-macrophage colony stimulating factor) was determined in TCGA datasets and five human glioma cell lines." (PMID 32390004, 2020). "Furthermore, when the glioma cells deficient in CSF2 were transplanted into the mouse brain, the TAM population was diminished, and the survival rate of tumor-bearing mice improved." (PMID 34439380, 2021). "Another study showed that the presence of CSF2/GM-CSF increases the migration ability of glioma cells and increases their resistance to apoptosis." (PMID 40727443, 2025). "In human gliomas, CSF2/GM-CSF stimulated microglia to increase the ability of tumor cells to infiltrate." (PMID 40727443, 2025). "We also found that CSF-1, CSF-2, and CSF-3 were all differentially upregulated in the murine glioma microenvironment." (PMID 39272914, 2024). "Colony-stimulating factor 2 (CSF-2), which is also called GM-CSF, is a glioma-derived CSF-2 that attracts and induces microglia to polarize into a pro-tumor phenotype." (PMID 37700840, 2023). "Although a few studies believe that CSF2 inhibits tumor progression, most studies have shown that it can stimulate various types of tumor cell growth and migration, including lung cancer, gliomas and skin carcinoma." (PMID 36437960, 2022). "Granulocyte–macrophage CSF (GM-CSF) drives microglia-dependent glioma invasion in vitro, while mRNA expression of its gene CSF-2 has been inversely associated with patient survival in GBM." (PMID 36403059, 2022). "Another study has demonstrated an increased migration capacity of glioma cells and resistance to apoptosis due to the presence of CSF2/GM-CSF." (PMID 34439380, 2021). "Effects of stable CSF2 knockdown in glioma cells or neutralising CSF2 or receptor CSF2Rα antibodies on glioma invasion were tested in vitro and in vivo." (PMID 32390004, 2020). "In the present study, we aimed to investigate the role of glioma-secreted CSF2 in controlling glioma–microglia interactions in vitro and in animal models." (PMID 32390004, 2020). "This demonstrates that glioma-derived CSF2 is important in supporting both accumulation and survival of microglia and macrophages." (PMID 32390004, 2020). "CSF2 knockdown or blockade of its signalling reduced microglia-dependent glioma invasion in microglia-glioma co-cultures." (PMID 32390004, 2020). "CSF2 knockdown in glioma cells or interference with CSF2 signalling using anti-CSF2 or anti-CSF2Rα antibodies significantly reduced microglia-dependent invasion in vitro." (PMID 32390004, 2020). "Intra-tumour infiltration of microglia and macrophages, evaluated with Iba1 staining, was decreased in CSF2-depleted LN18 gliomas compared to control shNeg tumours." (PMID 32390004, 2020). "Using RNA interference, we generated LN18 and U87 glioma cells stably depleted of CSF2 and for each glioma cell line we selected two clones (shCsf2) with the highest reduction of CSF2 mRNA and CSF2 protein levels, as determined by qPCR and ELISA, respectively." (PMID 32390004, 2020). "Similar effects were observed in the co-culture with immortalised human SV40 microglia (HM SV40), i.e. HM SV40-stimulated invasion was decreased in CSF2-depleted glioma cultures." (PMID 32390004, 2020). "Next, control (shNeg) and CSF2-depleted (shCSF2) LN18 glioma cells were intra-cranially implanted into striata of athymic mice." (PMID 32390004, 2020). "LN18 and U87 glioma cells showed the highest levels of CSF2 mRNA and produced abundant quantities of CSF2 protein, therefore these cells were employed for further experiments." (PMID 32390004, 2020).
glioma (continued). "We demonstrate that depletion of CSF2 in two human glioma cell lines reduces microglia-dependent glioma invasion in vitro and affects pro-tumorigenic polarisation of microglia." (PMID 32390004, 2020). "CSF2 knockdown in glioma cells results in impaired recruitment of microglia and macrophages in vivo, reduced glioma growth in mice and improved animal survival." (PMID 32390004, 2020). "Taken together, our results point to an important role of tumour-derived CSF2 in the pathology of human gliomas." (PMID 32390004, 2020). "Anti-CSF2 antibody significantly reduced the stimulating activity of human SV40 microglial cells on glioma invasion and to a lesser extent interfered with BV2 cells—dependent effects." (PMID 32390004, 2020). "Concordantly, the levels of CSF2 protein measured by ELISA were increased in culture supernatants of all tested human glioma cells." (PMID 32390004, 2020). "First, we compared the expression of CSF2 in human gliomas of different WHO grades and glioblastoma subtypes." (PMID 32390004, 2020). "Density of Iba1+ cells in the areas surrounding the encapsulated CSF2-depleted LN18 or U87 gliomas was, respectively, 2.8-fold or 1.4-fold lower than around the shNeg-containing HF." (PMID 32390004, 2020). "GCM from control LN18 and U87 cells (shNeg) induced IL10 and MYC expression in human microglia, while knockdown of CSF2 in glioma cells reverted IL10 mRNA to the basal levels." (PMID 32390004, 2020). "CSF2-depleted LN18 gliomas, when growing in nude mice, were less infiltrated by Iba+ cells and formed smaller tumours as compared to gliomas derived from shNeg cells." (PMID 32390004, 2020). "We previously reported that Csf2 produced by murine GL261 glioma cells supports microglia-dependent glioma invasion in vitro and tumour growth in mice." (PMID 32390004, 2020). "CSF2-depleted gliomas were smaller, attracted less microglia and macrophages, and provided survival benefit in tumour-bearing mice." (PMID 32390004, 2020). "Upstream regulators inhibited at the same early time point include CSF2, which supports M1 macrophage polarization, and CD38, whose loss attenuates glioma progression." (PMID 25952672, 2015). "In human glioma cells, CSF2 can promote cell growth and invasion." (PMID 35463955, 2022). "CSF2/GM-CSF triggered microglia to enhance tumor cells infiltration capacity in human glioma." (PMID 34439380, 2021). "Moreover, to confirm the role of CSF2 signalling in microglia-dependent glioma invasion, we employed neutralising antibodies against CSF2 or its receptor CSF2Rα." (PMID 32390004, 2020). "Survival of mice with CSF2-depleted gliomas was considerably prolonged." (PMID 32390004, 2020). "Moreover, we observed upregulation of IRF7 mRNA and Il1b mRNA in human microglia upon stimulation with CSF2-depleted LN18 or U87 glioma cells, respectively, relative to treatment with shNeg-conditioned medium." (PMID 32390004, 2020). "This may indicate a shift towards a pro-tumorigenic phenotype upon glioma cells-derived CSF2." (PMID 32390004, 2020). "CSF1/M-CSF signalling maintains proliferation and survival of monocytes through DAP12-β-catenin signalling pathway, and CSF2/GMCSF has been shown to regulate β-catenin signalling during myeloid lineage differentiation, and contribute to the survival of infiltrating monocytes in rat gliomas." (PMID 32390004, 2020). "Glioma progression and microglial activation are induced by tumor-derived macrophage colony-stimulating factor (M-CSF, CSF1) and granulocyte-macrophage colony-stimulating factor (GM-CSF, CSF2)." (PMID 40727443, 2025). "By synthesizing colony-stimulating factor (CSF2), glioma cells promote M2 polarization of macrophages and, consequently, tumor growth." (PMID 40191211, 2025). "Various inflammatory cytokines, including TNF, CSF2, IL1A, IL17A, IL6, and IFNG, were predictively inhibited in glioma samples exhibiting high CSMD1 expression." (PMID 38561856, 2024).
glioma (continued). "Tumor-derived macrophage colony stimulating factor (M-CSF, CSF1) and granulocyte macrophage colony stimulating factor (GM-CSF, CSF2) induce microglia accumulation and activation, as well as glioma progression." (PMID 34439380, 2021). "Knockdown of CSF2 in LN18 and U87 glioma cells strongly reduced BV2-dependent invasion as compared to shNeg controls." (PMID 32390004, 2020). "We demonstrate that CSF2/GM-CSF (produced by human LN18 and U87 glioma cells) stimulates microglia to enhance tumour invasion." (PMID 32390004, 2020). "In comparison to normal brain or NHA, the levels of CSF2 mRNA were upregulated in human LN18, LN229, T98, U251 and U87 glioma cells." (PMID 32390004, 2020). "After 2 weeks, the histological analyses of the implants showed that the outer membranes of the shNeg LN18 and shNeg U87 fibres were surrounded by Iba1+ cells, while significantly less cells migrated towards the HF with CSF2-depleted LN18 and U87 glioma cells." (PMID 32390004, 2020). "CSF2 depletion from both LN18 and U87 glioma cells blocked up-regulation of the anti-inflammatory IL10 expression and led to induction of IRF7 and IL1β mRNA levels in stimulated microglia." (PMID 32390004, 2020). "To study the impact of tumour-derived CSF2 on the brain microenvironment, we encapsulated human U87 and LN18 glioma cells into hollow fibres (HF) and transplanted them into the brains of immunocompetent mice." (PMID 32390004, 2020). "CSF2 secreted by glioma cells stimulated microglia accumulation around of LN18 and U87 gliomas encapsulated in hollow fibres in vivo." (PMID 32390004, 2020). "In conclusion, CSF1 and CSF2 are important factors involved in TAM recruitment and glioma progression and, therefore, the inhibitors of CSF1 and CSF2 signaling could be further explored for their potential beneficial effects in GBM." (PMID 34439380, 2021). "Interestingly, knockdown of CSF2 in glioma cells did not affect astrocyte activation and accumulation." (PMID 32390004, 2020). "Furthermore, using computational analysis with GO annotations, we identified functional groups among genes significantly enriched (adjusted p-value < 0.01) in gliomas with high CSF2 expression (FPKM > 0.05) relative to tumour samples with no CSF2 expression (FPKM = 0)." (PMID 32390004, 2020). "Silencing of CSF2 expression in LN18 and U87 glioma cells did not significantly affect cell proliferation and survival, as demonstrated by BrdU incorporation and MTT metabolism tests, respectively." (PMID 32390004, 2020).
asthma (122 papers, 2004 to 2025). "Several genes within the cytokine gene cluster on chromosome 5, specifically IL3, IL4, CSF2, TSLP, IL5, RAD50, and IL13, are recognized as potential asthma susceptibility genes due to their roles in inflammatory regulation among sensitized asthma patients." (PMID 41001556, 2025). "Among these proteins, MAPK3, IL6R, and CSF2—the most widely shared proteins—emerged as potential key regulators influencing the comorbidity of glucose metabolism dysregulation and asthma." (PMID 41300562, 2025). "PWAS identified IL6R, MAPK3, and CSF2 as the proteins most extensively shared between glycemic traits and asthma." (PMID 41300562, 2025). "Study has been shown that blockade of CSF2 signaling reduces airway inflammation and hyperresponsiveness in mouse models of environmentally induced lung injury and asthma." (PMID 36506032, 2022). "Here, we have analyzed the levels of cytokines such as IL-13, IFN-γ, TNF-α, IL-4, IL-5, and IL-1β and growth factors such as HGF, VEGF, and CSF2 or GM-CSF along with the estimation of serum S1P concentration in asthma patients compared with the healthy controls." (PMID 32637407, 2020). "Similarly, the growth factors that were found to be upstream of S1P signaling such as HGF, VEGF, and CSF2 were significantly (P < 0.01) increased in the serum of asthma patients compared to the healthy controls." (PMID 32637407, 2020). "The index SNP at chromosome 5q31, rs715285, maps to an intergenic region flanked by the genes CSF2 and P4HA2 and this region has been reported to be a susceptibility locus for multiple immune-related diseases including juvenile idiopathic arthritis, inflammatory bowel disease (IBD) and asthma." (PMID 25651891, 2015). "Restoring the levels of ZFP36L1 and ZFP36L2 in primary bronchial epithelial cells from patients with severe asthma decreased the mRNA expression of IL6, IL8 and CSF2." (PMID 37928904, 2023). "il-10, il-4, il-13, il-17a, il-2, tlr4, tlr9, ccl2, csf2, and vegfα are top 10 hub nodes in the PPI network, so we inquired the expression profiles of these genes in asthma from the GEO database." (PMID 33133221, 2020). "In the context of asthma and other inflammatory conditions, airway epithelial cells release factors such as CCL20, thymic stromal lymphopoietin (TLSP; also known as KLK11), IL-33, IL-25 and granulocyte-macrophage colony-stimulating factor (GM-CSF; also known as CSF2)." (PMID 39508347, 2024).